VDAC1 (voltage dependent anion channel 1)
Diseases named in the same sentence as VDAC1 in open-access papers (continued):
Sharing a sentence is not in itself a finding about the gene and the disease.
cancer (continued). "VDAC1 has been shown to participate in tumor progression in various cancers." (PMID 32210729, 2020). "VDAC1 is over expressed in cancer cells and silencing of it reduces cancer progression." (PMID 32327997, 2020). "As a transporter of metabolites, VDAC1 contributes to the metabolic phenotype of cancer cells." (PMID 32436862, 2020). "Indeed, its pivotal role in regulating cancer cellular energy, metabolism, and viability is also underscored by the findings that abrogation of VDAC1 expression reduced cellular ATP levels, cell proliferation, and tumor growth." (PMID 33114780, 2020). "Here, we provide insights into the multiple functions of VDAC1 and describe its involvement in several diseases, which demonstrate the potential of this protein as a druggable target in a wide variety of pathologies, including cancer." (PMID 33114780, 2020). "For example, the bad prognostic gene VDAC1 (voltage dependent anion channel 1), which is a multifunctional mitochondrial protein and an important regulator of cancer cell fate through its metabolic and energetic functions, was commonly up-regulated in all 3 datasets." (PMID 31913336, 2020). "The overexpressed VDAC1 contributes to cancer cell metabolism by facilitating the passage of essential metabolites, and delivering mitochondrial ATP directly to HK, which is also overexpressed in cancer (HK-I, HK-II)." (PMID 33114780, 2020). "Apoptosis can also be regulated by VDAC1, serving as an anchor point for mitochondria-interacting proteins, such as hexokinase (HK), Bcl2 and Bcl-xL, some of which are also highly expressed in many cancers." (PMID 32436862, 2020). "This mitochondrial protein is often overexpressed in several cancers, and it has been shown that VDAC1 depletion leads to a rewiring of cancer cell metabolism in breast cancer, lung cancer and glioblastoma, resulting in cell growth arrest, and tumor growth inhibition." (PMID 31921637, 2019). "In fact, we have demonstrated that VDAC1 is a novel target for cancer therapy." (PMID 31661894, 2019). "By targeting VDAC1, it is possible to hinder cancer cell apoptosis evading mechanisms." (PMID 31261935, 2019). "The VDAC1 is the main transport channel for metabolites and its overexpression in many cancers indicates that this mitochondrial pore contributes to the metabolic phenotype of cancer cells." (PMID 31803611, 2019). "The results thus show that VDAC1 depletion-mediated cancer cell metabolic reprograming involves a chain of events occurring in a sequential manner leading to a reversal of the unique properties of the tumor, indicative of the interplay between metabolism and oncogenic signaling networks." (PMID 31661894, 2019). "In this study, we asked whether silencing VDAC1 expression in cultured cancer cells would result in tumors showing rewired metabolism, altered TF levels, elimination of CSCs, and induction of differentiation." (PMID 31195298, 2019). "The complex set of effects resulting from VDAC1 depletion on a network of key regulators of cell metabolism, CSCs, TFs, and other factors, eventually leading cancer cells toward differentiation, indicates that all these changes are not random but rather occur as an ensemble." (PMID 31195298, 2019). "Furthermore, in cancer cells, HK2 associates with the voltage-dependent anion channel (VDAC1), located on the outer mitochondrial membrane, to protect malignant cells from mitochondrial membrane permeabilization." (PMID 31803611, 2019). "Furthermore, we demonstrated that VDAC1 represents an intersection between metabolism and cancer biology, with metabolism reprograming after VDAC1 silencing, not only inhibiting cell proliferation, but also directing the cell toward a differentiated state." (PMID 31195298, 2019). "Here, we demonstrated such a strategy using downregulation of VDAC1 expression in cancer cells." (PMID 31195298, 2019).
cancer (continued). "As depletion of CCP2 or inhibition of VDAC1 reverses the effects of RARRES1 depletion on energy balance and cell survival we conclude that RARRES1 modulation of CCP2-modulated tubulin-mitochondrial VDAC1 interactions is a fundamental regulator of cancer and stem cell metabolism and survival." (PMID 30899431, 2019). "In addition, the VDAC1–HKII complex can be targeted to trigger apoptosis in cancer cells overexpressing HKII." (PMID 31261935, 2019). "Additionally, treatment of cancer cells with myostatin promoted VDAC1 upregulation combined with downregulation and mitochondrial dissociation of HK." (PMID 30576325, 2018). "Hence, targeting the interactions of VDAC1 with anti‐apoptotic proteins (Bcl‐2, Bcl‐xL) or proteins supporting the metabolic requirements of cancer cells (HK‐I, HK‐II) is a promising strategy for the development of anticancer agents." (PMID 29698587, 2018). "Thus, by focusing on a single target, the mitochondria gatekeeper VDAC1, cancer-reprogrammed metabolism was reversed, leading to inhibited tumour growth in the three cancers tested." (PMID 30544833, 2018). "Indeed, this protein is overexpressed in many cancer types, and silencing of VDAC1 expression induces an inhibition of tumour development." (PMID 29593233, 2018). "Thus, for the first time, by depletion of the mitochondrial iron importer MFRN2 or of proteins of the ISC machinery, we were able to induce in normoxia a C-terminal truncation of VDAC1 similar to what was observed in cancer cells grown in hypoxia." (PMID 29596470, 2018). "In cancer and normal cells HK can only interact with VDAC1 isoform." (PMID 29998379, 2018). "Over the years, various anti-cancer molecules able to directly target to VDAC1 were proposed." (PMID 29682501, 2018). "For example, voltage-dependent anion channel 1 (VDAC1) is overexpressed in many cancer types." (PMID 28974231, 2017). "In this review, we highlighted the cancer–mitochondria–metabolism–apoptosis-VDAC1 axis." (PMID 28824871, 2017). "Finally, VDAC1-based peptides, interacting with purified HK, were shown to prevent HK protection against apoptosis (see VDAC1-Based Peptides As Potential Anti-Cancer Therapy)." (PMID 28824871, 2017). "Indeed, the requirement of VDAC1 for cancer development was demonstrated by silencing VDAC1 expression in cancer cells using specific si-RNA, resulting in marked inhibition of cancer cell proliferation both in vitro and in vivo." (PMID 29285267, 2017). "VDAC1, a key protein in cancer cell energy and metabolism homeostasis, is highly expressed in GBM." (PMID 28412744, 2017). "VDAC1, as a gatekeeper for the entry and exit of mitochondrial metabolites that also interacts with proteins that mediate and regulate the integration of mitochondrial functions with cellular activities, contributes to the metabolic phenotype of cancer cells." (PMID 28412744, 2017). "Therefore, VDAC1-based peptides can be considered as pan-drugs, representing potential therapeutic candidates for treating many cancers, including GBM." (PMID 28412744, 2017). "Introducing VDAC1’s N-terminal into cells was shown to inhibit both Bcl-2’s and Bcl-XL’s anti-apoptotic function, illustrating that VDAC1 could be a target for anti-cancer drugs." (PMID 28516063, 2017). "Thus, VDAC1 expression levels can serve as a biomarker for cancer development, treatment efficacy, and as a predictor of poor outcome." (PMID 28824871, 2017).
cancer (continued). "The causal nature of the relationship between VDAC1 expression levels and sensitivity to various treatments was illustrated in several studies where the correlation with drug efficacy suggests that numerous anti-cancer drugs and treatments act via the regulation of VDAC1 expression." (PMID 28824871, 2017). "VDAC1 also regulates apoptosis via interactions with apoptosis regulatory proteins, such as hexokinase, Bcl2 and Bcl-xL, some of which are also highly expressed in many cancers." (PMID 30542671, 2017). "VDAC1 is involved in the process of mitochondria-mediated apoptosis, mediating the release of apoptotic proteins and interacting with anti-apoptotic proteins, such as HK, Bcl-2 and Bcl-x, some of which are also highly expressed in many cancers, including GBM." (PMID 28412744, 2017). "We thus tested the possibility of interfering with the apoptosis-suppressive capacity of such proteins, using VDAC1-mimetic peptides to induce apoptosis in a broad range of cell lines derived from various cancers, regardless of the carried mutations." (PMID 28412744, 2017). "As the main transporter of ions, Ca2+, ATP, and other metabolites across the outer mitochondrial membrane, VDAC1 over-expression could offer numerous advantages to highly energy-demanding cancer cells." (PMID 29285267, 2017). "Thus, considering the high expression level of VDAC1 in tumors and the specificity of si-hVDAC1 in inhibiting cancer cell and tumor growth, silencing VDAC1 expression can be considered as a novel strategic therapeutic approach to treat cancer." (PMID 28824871, 2017). "The observation that VDAC1 is over-expressed in many cancers suggests that the protein may play a pivotal role in cancer cell survival." (PMID 28824871, 2017). "Importantly, we have been able to develop VDAC1-based peptides, which can interfere with these interactions, leading to impaired cell metabolism and apoptosis (see VDAC1-Based Peptides As Potential Anti-Cancer Therapy)." (PMID 28824871, 2017). "The coupling between VDAC1 and elevated levels of HK leads to a high glycolytic rate resulting in enhanced generation of lactate, a key component in promoting cell growth and protecting against mitochondria-mediated cell death in cancer cells." (PMID 28713289, 2017). "Though, VDAC1 is over-expressed in many cancer types, and its silencing inhibits tumor development." (PMID 28512624, 2017). "Importantly, VDAC1 knockdown reduced cancer cell migration in vitro and suppressed tumor growth in vivo." (PMID 28848710, 2017). "A new proposed mechanism of pro-apoptotic drug action, namely Ca2+-dependent enhancement of VDAC1 expression, provides a platform for developing a new class of anticancer drugs modulating VDAC1 levels via the promoter and for overcoming the resistance of cancer cells to chemotherapy." (PMID 28443244, 2017). "As the regulation of VDAC1 by Mcl-1 also stimulates cancer cell migration, Mcl-1 inhibitors may not only be useful to eliminate Mcl-1-dependent cancers by provoking cell death but also by counteracting metastasis." (PMID 28516063, 2017). "VDAC-1 over-expression was also observed in several cancer cells." (PMID 28407688, 2017). "The results showed that cancer tissues with positive VDAC1 immunoreactivity exhibited deep stromal invasion (>10 mm in depth of stromal invasion, p<0.001, OR: 4.14 and 95% CI: 1.80-9.88) and large tumor size (>4 cm in diameter, p=0.001, OR: 3.77 and 95% CI: 1.60-9.00)." (PMID 26716410, 2016). "Reducing VDAC1 inhibits cancer cell growth and tumor development in vivo." (PMID 26716410, 2016). "To date, no studies have explored the potential diagnostic value of VDAC1 in cancer, and particularly, in CLL." (PMID 27078856, 2016). "The role of VDAC1 as oncogene was found in many cancer lines or tissues." (PMID 27304056, 2016). "VDAC1 also contributes to cancer cell metabolism via its binding to HK." (PMID 27078856, 2016).
cancer (continued). "Thus, determination of VDAC1 expression levels can be useful as a molecular biomarker to predict cancer development and treatment efficacy." (PMID 27289382, 2016). "This could counteract the favorable microenvironment that gives cancer cells a growth advantage and thereby disrupts the balance between life and death, which is controlled by VDAC1." (PMID 27625993, 2016). "We examined the action by which VDAC1 exerted its effect on the cancer cells and investigated whether the presence of VDAC1 had correlations with MMP, cell cycle, autophagy protein expressions and reactive oxygen species (ROS)." (PMID 26716410, 2016). "VDAC1 is expressed in all mammalian cells and at high levels in cancer cells." (PMID 26716410, 2016). "VDAC1 over-expression offers numerous advantages to cancer cells, given its multi-functionality." (PMID 27078856, 2016). "In addition, VDAC1 also binds Bcl-2 and Bcl-xL, anti-apoptotic proteins expressed in many cancer cells, and impacts their cell-saving function." (PMID 27289382, 2016). "Thus, the VDAC1–HK complex already represents a target for cancer therapy, using, for example, specific VDAC1-based peptides that disrupt the connections between these proteins." (PMID 27625993, 2016). "We also silenced the VDAC1 gene in SiHa and CaSki cancer cells to examine the influence of VDAC1 on cisplatin cytotoxicity, and found that when the VDAC1 gene had been silenced, the cell cytotoxicity of cisplatin was significantly enhanced at different concentrations of cisplatin." (PMID 26716410, 2016). "Indeed, this protein is over-expressed in many cancer types, and silencing of VDAC1 expression induces an inhibition of tumor development." (PMID 27304056, 2016). "VDAC1 also regulates apoptosis as an anchor point for mitochondria-interacting proteins, such as hexokinase (HK), Bcl2 and Bcl-xL, some of which are highly expressed in many cancers." (PMID 27304056, 2016). "The role of VDAC1 in cancer has only just started to be investigated." (PMID 26322231, 2015). "Metabolic reprogramming in cancer cells may be regulated by VDAC1 through vascular destabilization and inflammation." (PMID 26322231, 2015). "A possible mechanism(s) of surface structures discrimination between normal and cancer cells mitochondria by MJ seems to occur, and it is probably related to the overexpression and tight binding of hexokinase(s) (HK) to the VDAC1 pore in the outer mitochondrial membranes (OMM) in cancer cells." (PMID 24648844, 2014). "In total, we collected 1,357 cancer-related genes that don’t interact with VDAC1." (PMID 25333947, 2014). "The studies reviewed above have demonstrated the pivotal roles of mitochondria and VDAC1 in cancer." (PMID 23233904, 2012). "In addition, VDAC1 mediates cholesterol transport and distribution in the mitochondrial membrane, with cancer cells exhibiting several fold higher cholesterol levels than do healthy cells." (PMID 23233904, 2012). "Accordingly, anti-cancer strategies that specifically up-regulate VDAC1 levels in cancer cells may activate the mitochondrial apoptotic pathway, with concomitant benefit to the patient." (PMID 23233904, 2012). "Together, these findings indicate that over-expression of VDAC1 in cancer cells could contribute to the high glycolytic phenotype seen." (PMID 23233904, 2012). "VDAC1 expression in several cancer cell lines was higher than in the control fibroblast cell line." (PMID 23233904, 2012). "Thus, VDAC1-based peptides, targeting the anti-apoptotic activity of Bcl-xL and Bcl2, can serve as potential cancer therapeutics." (PMID 23233904, 2012). "As a metabolite transporter, VDAC1 contributes to the metabolic phenotype of cancer cells." (PMID 23233904, 2012).
cancer (continued). "Among the complex array of genetic changes accompanying cancer development, all cancerous cells develop altered metabolism, with VDAC1 and HK playing important functions in this metabolic reprograming (see The Interaction of VDAC1 with Hexokinase Regulates Cell Bioenergetics and Apoptosis)." (PMID 23233904, 2012). "Cancer cells with low VDAC1 induced by RNA interference exhibit a defect in cell growth in vivo." (PMID 21297950, 2011). "Our findings suggest that expression levels of VDAC1 could be a factor predictive for tumour sensitivity to therapeutic TRAIL receptor agonists in a subset of cancers." (PMID 20646307, 2010). "Schwann cells may facilitate cancer progression through VDAC1." (PMID 40052442, 2025). "In summary, VDAC1 has been found to interact with over 100 proteins involved in diverse cellular processes such as metabolism, survival, proliferation, signaling, migration, and more—functions that are essential for both normal physiology and cancer progression." (PMID 41006687, 2025). "The results reflect the complex remodeling of the TME by cancer cells in the tumor and suggest that cancer metabolic reprogramming via VDAC1 depletion targets both the cancerous and stromal compartments within a tumor—a relation that may offer therapeutic potential." (PMID 39456237, 2024). "Additionally, VDAC1 depletion led to changes in the expression of transcription factors (TFs), metabolic processes and the epigenetic landscape, affecting signaling pathways related to cancer hallmarks." (PMID 39272828, 2024). "Furthermore, VDAC1 inhibition by siRNA induces cancer cell apoptosis, suggesting that siRNAs could be a target for cancer therapy." (PMID 38172597, 2024). "Future studies could explore Metformin as a treatment for cancers with high VDAC1 expression." (PMID 39627451, 2024). "Using MRI to monitor the lung tumors, we found that inhibiting VDAC1 expression in this mouse model led to significant changes: reprogramming of cancer cell metabolism, reduced tumor growth, alterations in the tumor microenvironment, and elimination of cancer stem cells (CSCs)." (PMID 39272828, 2024). "This review examines how targeting VDAC1 could influence high-energy demanding cancer cells." (PMID 39456237, 2024). "Therefore, this study suggests that inhibiting the overexpression of VDAC1 could be a novel therapeutic target for cancer treatment." (PMID 38989148, 2024). "Notably, genes associated with the glycolysis/gluconeogenesis pathway including LDHA —whose overexpression in cancer is associated with proliferation and malignancy— and several glycolytic genes (e.g. HK1, VDAC1, and VDAC2) were only upregulated in LB fHER2− tumours and derived CLs." (PMID 36220861, 2022). "Furthermore, the potential characteristic information and molecular mechanisms of VDAC1 in the onset or prognosis of cancers were explored, such as gene expression, survival analysis, alteration, phosphorylation, immune infiltration, and related cellular signal pathways." (PMID 35958281, 2022). "VDAC1 might be served as a novel pharmacological target for anti-cancer therapeutics." (PMID 35729567, 2022). "Thus, a pan-cancer study of VDAC1 was performed, including gene expression and alteration, protein phosphorylation, survival prognosis analysis, immune infiltration, or molecular pathway enrichment in different tumor types based on the TCGA, GEO, and CPTAC datasets." (PMID 35958281, 2022). "The VDAC1 N-terminal-derived CPP might have therapeutic potential for cancer and other diseases." (PMID 36291596, 2022). "Therefore, in this study, we explored the mitochondrial apoptosis mediated by PGC1α through the HSP70/HK2/VDAC1 signaling pathway, which may provide a new strategy for inducing apoptosis of cisplatin-resistant cancer cells." (PMID 33802591, 2021).